RNU6-499P (RNA, U6 small nuclear 499, pseudogene)
Gene: Small nuclear RNA gene on chromosome 4 (82,174,547 to 82,174,653, forward strand). Ensembl gene ENSG00000202485.
Homologues: Orthologues: chimpanzee U6 (90% identical). Paralogues in human: RNU6-770P (77% identical), RNU6-98P (77% identical), RNU6-1084P (76% identical), RNU6-1249P (76% identical), RNU6-1260P (76% identical), RNU6-144P (76% identical), RNU6-188P (76% identical), RNU6-54P (76% identical), RNU6-684P (76% identical), RNU6-128P (75% identical), RNU6-1316P (75% identical), RNU6-21P (75% identical), and 1285 more.